IL6 (interleukin 6)
Diseases named in the same sentence as IL6 in open-access papers (continued):
Sharing a sentence is not in itself a finding about the gene and the disease.
ischemic stroke (continued). "Other cytokines involved in the pathogenesis of neuro-inflammation behave similarly like the pro-inflammatory cytokine interleukin-6 (IL-6) and the leukocyte chemotactic activating cytokine, IL-8, during hemorrhagic and ischemic stroke." (PMID 31295895, 2019). "Studies have found that the expression levels of IL-4, IL-5, IL-6, and IL-10 are increased remarkably in the damaged hemisphere after ischemic stroke." (PMID 31164999, 2019). "Recent studies have demonstrated that IL-6 production was elevated during ischemic stroke conditions, which was consistent with our results." (PMID 31652447, 2019). "Considering IL6, it has been reported that pre-treatment with tocilizumab, a monoclonal antibody against IL6 in a rat model of ischemic stroke, prevents neuronal cell apoptosis." (PMID 30057552, 2018). "Inflammatory cytokines such as TNF-α, IL-1β, and IL-6 play pivotal roles in the pathogenesis of ischemic stroke." (PMID 29234386, 2017). "Brazilein is an important pro-inflammatory cytokines inhibitor, it has been demonstrated a neuroprotective effect though suppress TNFα and IL6 mRNA expressions, the treatment prospects on ischemic stroke have been widely reported." (PMID 27672514, 2016). "Previous studies showed several interleukins (IL1, IL6, IL8, TNF, etc.)play a crucial role in immune processes and strongly associated with ischemic stroke." (PMID 27672514, 2016). "An increasing number of experimental observations showed that IL6 plays a central role in the pathogenesis of several ischemic cardiovascular disorders, including ischemic stroke." (PMID 27672514, 2016). "A recent report suggested that IL6 is essential for the promoting effects of social interaction on the neurogenesis as well as long-term functional recovery after ischemic stroke." (PMID 27672514, 2016). "But also pro-inflammatory mediators such as C-reactive protein (CRP) and Interleukin-6 (IL-6) are increased in ischemic stroke patients who develop an infection." (PMID 25613713, 2015). "The acute-phase response, characterized by elevated plasma concentrations of IL-6, C-reactive protein and neutrophil leukocytosis, is induced within hours of ischemic stroke." (PMID 24349350, 2013). "According to present study the cerebrospinal fluid contents of interleukin-6 and nitrates seem to be the most reliable prognostic factors in acute phase of ischemic stroke." (PMID 21450100, 2011). "Contrary to our findings, Hughes and colleagues (2006) reported that IL-6 and IL-1β were significantly reduced in the brains of Ccl2-/- mice after induction of ischaemic stroke." (PMID 20942978, 2010). "Clinical studies have shown that IL-6 levels peak within 12 h of ischemic stroke and stimulate other protective mediators." (PMID 19421412, 2009). "We found significantly higher levels of salivary pro-inflammatory cytokines (IL-1β, TNF-α, TNF-β), anti-inflammatory cytokines (IL-1ra, TRAIL), Th1 cytokines (IFN-γ and IL-12 (p40)), and Th2 cytokines (IL-6) in patients with ischemic stroke compared to healthy participants." (PMID 40520895, 2025). "Additionally, pre-conditioning with IL-6 increases the efficacy of cell transplantation therapy in ischemic stroke by protecting neural stem cells (NSCs) from reperfusion injury." (PMID 40305179, 2025). "After ischemic stroke, IL-6 elevation has been shown to correlate with increased CRP levels." (PMID 41300897, 2025). "The role of IL-6 in ischemic stroke pathophysiology is relatively well established." (PMID 41221512, 2025). "In the setting of an ischemic stroke, vitamin D may mitigate neuroinflammation by downregulating pro-inflammatory mediators such as interleukin 6 (IL-6) and tumor necrosis factor alpha (TNF-α), potentially limiting secondary neuronal damage." (PMID 40142657, 2025). "Clinically, IL-6 is among the most studied biomarkers in ischemic stroke." (PMID 40869247, 2025).
ischemic stroke (continued). "Itgam, as one of the potential core therapeutic targets in patients with ischemic stroke, may play a role by regulating the secretion of key inflammatory factors, IL-1β, IL-6 and TNF-α, and influencing neuronal apoptosis." (PMID 41181154, 2025). "Furthermore, ischemic stroke also stimulate glial cells and macrophages, giving rise to the secretion of many inflammatory cytokines such as IL-6 and TNF-α, leading to inflammation and neuronal cell death." (PMID 39683536, 2024). "Prospective studies have shown that high levels of IL-6 in community-dwelling individuals are directly linked to an increased risk of developing ischemic stroke in the long run, regardless of traditional vascular risk factors." (PMID 38895632, 2024). "Furthermore, individuals receiving edaravone dexborneol injection exhibited lower expression levels of interleukin (IL)-1β, IL-6, and IL-17, along with higher levels of IL-4 and IL-10 expression during the acute phase of ischemic stroke (P < 0.05)." (PMID 38902691, 2024). "Currently, blood biomarkers may be used to predict and diagnose ischaemic stroke, including B-type natriuretic peptide, interleukin-6, D-dimer, total cholesterol, interleukin-1β, and high-density lipoprotein." (PMID 36644582, 2023). "In addition, chrysophanol was reported to promote neurological recovery by downregulating the expression of IL1 and IL6 to limit microglia-mediated neuroinflammation and inhibit ROS production after ischemic stroke in mice." (PMID 37264383, 2023). "IL-6 is the main driver of the production of the pro-inflammatory cytokine of CRP production in the liver, which is associated with an increased risk of ischemic stroke and is involved in the process of ischemic brain injury by binding to IL-6R to initiate intracellular signaling." (PMID 38104193, 2023). "Presence of CHIP is associated with the atherosclerotic cardiovascular disease through the activation of the interleukin 6 (IL-6) pathway; however, its role on unfavorable functional outcomes in different etiologies of ischemic stroke remains unclear." (PMID 38104193, 2023). "Together, this evidence suggests that targeting IL-6 with MAb may be an adjuvant treatment for preventing ischemic stroke in patients with carotid atherosclerosis." (PMID 37762627, 2023). "IL6 in particular is considered a prognostic marker in ischemic stroke." (PMID 35566778, 2022). "In addition, IL-6 is related to the inflammation, which contributes to both damage and recovery process after ischemic stroke." (PMID 35173738, 2022). "Further subgroup analysis of colchicine and other drugs targeting the central IL-6 inflammatory signaling pathway showed that colchicine can significantly reduce the incidence of ischemic stroke (RR 0.48 0.29–0.79, P = 0.004, I2 = 20%, Pheterogeneity = 0.29) compared with other drugs." (PMID 35246052, 2022). "VTN blood levels increase only in female mice 24 h after an ischemic stroke and exacerbate brain injury through IL‐6‐driven inflammation, but the VTN induction mechanism is unknown." (PMID 35531929, 2022). "Finally, we found that metyrapone (an inhibitor of GC synthesis) demonstrated a protective effect after ischemic stroke with reduced IL-6 expression." (PMID 35784349, 2022). "Moreover, the KEGG Mapper results further showed that IL-1β, TNF-α, IL-6, and IL-4 are core potential targets involved in Epimedium-mediated neuroinflammation following ischemic stroke." (PMID 36338345, 2022). "Moreover, it is also reported to suppress inflammation (even the production of TNFα and IL6) and is involved in the protection of the brain from the deleterious effects of ischemic stroke." (PMID 36572898, 2022). "Reduction of IL-6 expression, but not the other cytokines, in the ischemic brain of diabetic mice treated with metyrapone indicates that IL-6 may be a critical cytokine in mediating the impact of an altered HPA axis in ischemic stroke." (PMID 35784349, 2022).
ischemic stroke (continued). "The critical role of IL-6 in ischemic stroke has been shown." (PMID 35784349, 2022). "In addition, IL-16 promotes the production of inflammatory cytokines such as TNF-α, IL-1β, and IL-6, which has key effects in immune responses after ischemic stroke." (PMID 35173738, 2022). "Also, the plasma IL-6 level is a predictor of recurrences as well as of the prognosis of patients with ischemic stroke." (PMID 34683106, 2021). "IL6 trans-signaling, assessed by the B/T ratio, is associated with an increased risk of ischemic stroke in patients without known AF." (PMID 34372806, 2021). "A report describing two patients with POEMS syndrome, Castleman disease, and recurrent ischemic strokes has speculated that interleukin-6 (IL-6) might play an important role in the occurrence of cerebral vasculopathy and ischemic stroke." (PMID 34167480, 2021). "We aimed at investigating the role of IL6 trans-signaling in ischemic stroke in relation to AF." (PMID 34372806, 2021). "Statins attenuate IL-6 and enhance ACE2, thereby mitigating the risk of CAD and ischemic stroke." (PMID 34705851, 2021). "Our findings fit very well with a substantial body of data linking IL-6 to ischemic stroke." (PMID 33420113, 2021). "Atorvastatin could decrease the concentration of IL-6 and TNF-α and improved the outcome of ventilator-associated pneumonia in patients with ischemic stroke." (PMID 33728336, 2021). "Pro-inflammatory IL6 trans-signaling, estimated by the B/T ratio, is associated with ischemic stroke in individuals without AF." (PMID 34372806, 2021). "Similar to the result, we hypothesize that alterations of TNF-α, IL-1β, and IL-6 concentrations in CSF are more suitable to represent inflammatory response after ischemic stroke." (PMID 34257822, 2021). "Even though IL-6 is a proinflammatory protein, researchers proposed that it has an essential function during an ischemic stroke because of its proinflammatory properties in the first step of ischemia, but also playing a neurotrophic role in the successive stages." (PMID 32899616, 2020). "It shows that IL‐6 contributes to determination of severity of ischemic stroke and may be useful in predicting patient prognosis." (PMID 32583980, 2020). "The evidence from the present study suggests that IL‐6 contributes to the determination of the severity of ischemic strokes and may be useful in predicting prognosis." (PMID 32583980, 2020). "Also, previous studies found a significant correlation between IL-6 levels and the outcome and mortality rate of ischemic stroke patients." (PMID 30915140, 2019). "Another cytokine involved in pro-inflammatory response after ischemic stroke is interleukin-6." (PMID 31722731, 2019). "The biological role of IL-6 in ischemic stroke remains uncertain." (PMID 30828313, 2019). "Astrocytic IL-6 mediated the immune response toward Tregs and Th2 bias in the ischemic hemisphere and thus contributed to the promoting effects of hyperforin on neuroangiogenesis after ischemic stroke." (PMID 31133816, 2019). "IL-6 is another pro-inflammatory cytokine that is involved in the pathogenesis of ischemic stroke." (PMID 31652447, 2019). "Recent studies revealed that despite of IL-1 and IL-6, different isoforms of transforming growth factors-β (TGFβ) may be efficient as pro-inflammatory factors in immune response after ischemic stroke." (PMID 31722731, 2019). "Our observation that ischemic strokes are associated with a significant increase in DAD score and lung ultrastructural changes might be explained by higher levels of TNF-α and IL-6 in the plasma and lungs, and of TNF-α in BALF." (PMID 30290827, 2018). "In-vitro experiments revealed that the phagocytic capability of alveolar macrophages was reduced and the expression of TNF-α and IL-6 was increased in alveolar macrophages isolated from naïve rats only after exposure to serum from rats that had experienced ischemic stroke." (PMID 30290827, 2018).
ischemic stroke (continued). "Studies also have shown that lesion volume correlates with IL-6 level after ischemic stroke." (PMID 27682880, 2017). "Thus, our results reveal a previously uncharacterized property of HMGB1/IL-6 signaling pathway in EE-mediated angiogenesis and functional recovery after ischemic stroke." (PMID 28845299, 2017). "Elevating serum levels of IL-6 is very common in patients with Castleman’s disease, and it’s well known as a key factor of the systemic inflammatory and a predictor of poor outcome of ischemic stroke." (PMID 29179528, 2017). "IL-6 may play a pivotal role in the etiologic link between Castleman’s disease and the occurrence of cerebral vascopathy and ischemic stroke." (PMID 29179528, 2017). "In addition, the elevated levels of IL-17, IL-33 and IL-6 were found in the plasma of patients with ischemic stroke, as well as in the supernatants of the cell monocyte stimulated by HMGB1." (PMID 27040385, 2016). "It was identified that CXCL10 and IL-6 may have important roles in the progression of ischemic stroke and thus may be used as specific therapeutic molecular targets." (PMID 25333814, 2015). "Among them, notable examples include fibrinogen, serum amyloid A (SAA), interleukin-6 (IL-6), and lipoprotein-associated phospholipase A2 (Lp-PLA2), which was recently approved by United States Food and Drugs Administration as a predictor of ischemic stroke." (PMID 25960621, 2015). "Also, it has been shown that IL-6 is an indicator that could predict mortality both one year and two years after ischemic stroke." (PMID 37260778, 2023). "Additionally, IL-6 aids CNS post-traumatic recovery via endothelial cell repair, which may improve vascular reconstruction or angiogenesis following ischemic stroke." (PMID 36793730, 2023). "However, large studies are needed to confirm the finding and to determine if serum IL-6 levels could be used as a predictor of prognosis for patients with ischemic strokes." (PMID 37342100, 2023). "Indeed, the role of IL-6 in course of ischemic stroke is still under scientific debate." (PMID 36745280, 2023). "Epimedium treatment significantly inhibited the expression of IL-1β, TNF-α, and IL-6 and enhanced the expression of IL-4, which suggests that Epimedium exerted its neuroprotective effects via regulating the expression of proinflammatory and anti-inflammatory cytokine following ischemic stroke." (PMID 36338345, 2022). "Recently, higher circulating IL-6 levels in community-dwelling individuals have been shown to be linearly associated with a higher long-term risk of incident ischemic stroke, and independent of conventional vascular risk factors, they have been reported in several other studies." (PMID 36119741, 2022). "Also, many genes encoding chemokines, cytokines and chemokine receptors, which are involved in neuroinflammatory processes in ischemic stroke, were regulated, including Cxcr2 in endothelial cells, Ccl5, Il11 and Il6 in pericytes, Lcn2 in astrocytes and pericytes, and Il1rn in microglia." (PMID 35752654, 2022). "However, we found that ischemic stroke increases the plasma level of IL-6." (PMID 36085043, 2022). "Moreover, IL-19 treatment can significantly reduce the up-regulation of TNF-α and IL-6 mRNA expression after ischemic stroke, inhibit the increase of microglia, macrophages, CD4+ T cells, CD8+ T cells, and B cells, and suppress the activation of macrophages and neutrophils." (PMID 35173738, 2022). "The membrane-bound IL-6R is composed of two subunits: the IL-6R-α chain (to which IL-6 binds) and the assisting transmembrane signaling subunit, glycoprotein 130 (gp130), which is the intra-cellular signal transducer and abundantly expressed during ischemic stroke." (PMID 34691061, 2021). "Moreover, in the present study we aimed at analyzing the risk of ischemic stroke associated with IL6 trans-signaling in individuals with and without AF." (PMID 34372806, 2021).
ischemic stroke (continued). "Here we demonstrate that IL6 trans-signalling, mirrored by the B/T ratio > median, is associated with increased risk of ischemic stroke albeit the association could not be shown in the small group of participants with AF nor with the risk of AF specifically." (PMID 34372806, 2021). "In the acute phase of ischemic stroke, resident microglia and recruited macrophages assume an M2 phenotype, and the immune-mediated inflammatory response is activated, resulting in the secretion of a number of inflammatory cytokines (IL-6, IL-1β, and TNF-α and the proteolytic enzymes MMP 3 and 9)." (PMID 34276353, 2021). "Therefore, we propose that astrocytic IL-6 may be involved in the promoting effects of antidepressant hyperforin on neuroangiogenesis and functional recovery after ischemic stroke." (PMID 31133816, 2019). "Moreover, some specific ILs such as IL-6 might be an independently predictive biomarker for future mortality in the elderly after an ischaemic stroke." (PMID 27679860, 2016). "Additionally, the induction of proinflammatory cytokines, such as interleukin-8, tumor necrosis factor-α and interleukin-6, may be more frequent in adults <50 years with a history of ischemic stroke." (PMID 27355475, 2016). "In addition, IL-6 concentrations affect clinical outcomes in ischemic stroke." (PMID 25295149, 2014). "For example, in a mouse model of ischemic stroke, microglia‐specific PGC‐1α overexpression suppresses NLRP3 inflammasome activation; reduces TNF‐α, IL‐1β, and IL‐6 production; enhances mitophagy; and significantly improves neurological outcomes." (PMID 41517974, 2026). "For example, reversing dysbiosis through the ingestion notoginseng saponins restored BBB integrity via increased occludin and Zo1 expression, and reduced proinflammatory cytokine expression (IL-1B, IL-6, TNF) in a rodent model of ischemic stroke." (PMID 40485663, 2025). "In ischemic stroke, microglia polarize into distinct phenotypes: pro-inflammatory M1 (secreting TNF-α, IL-1β, IL-6) and pro-angiogenic M2 (releasing IL-10, TGF-β, VEGF)." (PMID 40988927, 2025). "During ischemic stroke, microglia produce pro-inflammatory cytokines such as tumor necrosis factor (TNF), interleukin 1 beta (IL1β), interleukin 6 (IL6), and proteolytic enzymes such as matrix metalloproteinase 9 (MMP9)." (PMID 40676515, 2025). "Cytokines play a pivotal role in the inflammatory response following an ischemic stroke with TNF-α, IL-1β, IL-6, and IL-10 being particularly significant." (PMID 40095189, 2025). "In our study, the direct proportional correlation between IL-6, TNF-alpha, and NIHSS scores further emphasizes the role of these inflammatory markers in the early and late stages of ischemic stroke." (PMID 39859987, 2025). "Certain subgroups of ischemic stroke patients had the lowest expression levels of SOD, BMAL1, and SIRT1, whereas other subgroups had the highest levels of MDA, IL-6, and TNF-α." (PMID 41567643, 2025). "Clinical studies have associated oxidative stress and pro-inflammatory cytokines such as IL-1β, IL-6, and TNF-α with poor outcomes in ischemic stroke patients." (PMID 39596503, 2024). "As the results showed, there was increased production of pro-inflammatory cytokines, including TNF-α, IL-6, and IL-1β, in the CMI+PT group compared to the PT group on the first day after ischemic stroke." (PMID 38216560, 2024). "This study found a downward trend in BMAL1 and SIRT1 expression along with increased activation of oxidative stress (MDA) and inflammatory factors (IL-6, TNF-α) in patients with early-onset ischemic stroke." (PMID 38245621, 2024). "Following ischemic stroke, MCP-1−/− mice exhibit reduced expression of IL-1β, IL-6, and G-CSF, which helps prevent further damage to the blood–brain barrier in mice." (PMID 39649720, 2024). "Pro-inflammatory cytokines, including IL1α, IL1β, IL6, TNFα, and the number of CD16 + and CD206 + microglia (especial CD16 + microglia), increased after ischemic stroke." (PMID 38287382, 2024).